LGI4 (leucine rich repeat LGI family member 4)
Description:
Component of Schwann cell signaling pathway(s) that controls axon segregation and myelin formation (By similarity).
Synonyms: LGIL3; AMC1; AMCNMY
Tractability: Antibody: UniProt places it where antibodies can reach, with high confidence; its Gene Ontology location is reachable by antibodies, with high confidence; UniProt predicts a signal peptide or a membrane-spanning region.
Gene: Protein-coding gene on chromosome 19 (35,124,510 to 35,142,451, reverse strand). Ensembl gene ENSG00000153902.
Subcellular location: Secreted
Subcellular location (Human Protein Atlas): Golgi apparatus; Predicted to be secreted
Pathways (Reactome):
Developmental Biology: LGI-ADAM interactions
Gene Ontology:
Biological process: regulation of myelination; myelination in peripheral nervous system; neuron maturation
Cellular component: extracellular region; non-collagenous component of interstitial matrix
Genetic constraint (gnomAD): Loss-of-function variants: 35 observed, 36.98 expected, observed/expected ratio (o/e) 0.95, 90% interval 0.72 to 1.25. The synonymous counts are far from expectation, so gnomAD's model fits this gene poorly and the ratio says little. Missense variants: 675 observed, 595.05 expected, observed/expected ratio (o/e) 1.13, 90% interval 1.06 to 1.21. Synonymous variants: 343 observed, 264.51 expected, observed/expected ratio (o/e) 1.3, 90% interval 1.19 to 1.42.
Homologues: Orthologues: chimpanzee LGI4 (99% identical), dog LGI4 (94% identical), macaque LGI4 (93% identical), pig LGI4 (92% identical), guinea pig LGI4 (91% identical), mouse Lgi4 (88% identical), rabbit LGI4 (85% identical), rat Lgi4 (83% identical), zebrafish lgi1b (49% identical), zebrafish lgi1a (47% identical), Drosophila melanogaster kek3 (18% identical), Drosophila melanogaster Con (14% identical), and 6 more. Paralogues in human: LGI1 (49% identical), LGI3 (42% identical), LGI2 (41% identical), LRIG1 (19% identical), LRIG2 (18% identical), LRIG3 (18% identical), LGR6 (16% identical), ELFN1 (15% identical), ELFN2 (15% identical), TRIL (15% identical), LGR5 (15% identical), LGR4 (15% identical), and 10 more.
Diseases named in the same sentence as LGI4 in open-access papers:
LGI4 is named in the same sentence as 15 diseases in open-access papers, as found by Europe PMC text mining. Sharing a sentence is not in itself a finding about the gene and the disease. The quoted sentences say what the papers report.
Camptodactyly (1 paper, 2021). The distal interphalangeal joint and/or the proximal interphalangeal joint of the fingers or toes cannot be extended to 180 degrees by either active or passive extension. "Biallelic LGI4 LoF variants may cause a rare form of neurogenic Arthrogryposis multiplex congenita due to a specific myelin defect, a severe disease characterized by prenatal onset (reduced fetal mobility, club feet, camptodactyly), which often results in stillbirth." (PMID 33727708, 2021).
Dystonia (1 paper, 2020). An abnormally increased muscular tone that causes fixed abnormal postures. "Variants in LGI4 cause arthrogryposis multiplex congenital; variants in PLEKHG2 cause mental retardation, dystonia and microcephaly; and those in PLEC1 have been shown to be involved in a renal disease (nephrotic syndrome)." (PMID 32340215, 2020).
glioma (1 paper, 2013). A benign or malignant brain and spinal cord tumor that arises from glial cells (astrocytes, oligodendrocytes, ependymal cells). "The requirement for LGI4 for embryonic enteric glial cell and satellite cell proliferation contrasts with that of LGI1 for glioma cells as LGI1 inhibits proliferation of glioma cells." (PMID 23713523, 2013).
melanoma (1 paper, 2015). A malignant, usually aggressive tumor composed of atypical, neoplastic melanocytes. "The microarray results indicated that microenvironmental cues can trigger switching of melanoma cells to a neural stem cell-like pattern, as six genes related to neural stem cell and neural stem cell niche biology were upregulated: SOX2, ID4, GFRA2, S100A4, LGI4, and GJB1." (PMID 25642713, 2015).
LGI4 also shares sentences with these, for which no sentence is quoted: arthrogryposis multiplex congenita (1 paper); atrial fibrillation (1); epilepsy (1); infection (1); microcephaly (1); nephrotic syndrome (1); Neurogenic arthrogryposis multiplex congenita (1); renal disease (1); tumour (1); type 1 diabetes (1); viral myocarditis (1).